BMAL1 (basic helix-loop-helix ARNT like 1)
Diseases named in the same sentence as BMAL1 in open-access papers (continued):
Sharing a sentence is not in itself a finding about the gene and the disease.
Tremor (2 papers, 2015 to 2024). An unintentional, oscillating to-and-fro muscle movement about a joint axis. "Other work has demonstrated a reduction in the time-dependent variation of BMAL1 expression, and an association between a BMAL1 variant and the tremor-dominant subtype of PD." (PMID 37943299, 2024).
triple-negative breast carcinoma (2 papers, 2020 to 2021). An invasive breast carcinoma which is negative for expression of estrogen receptor (ER), progesterone receptor (PR), and human epidermal growth factor receptor 2 (HER2). "Moreover, BMAL1 regulates pyruvate metabolism in MDA-MB-231 cells, and inhibition of BMAL1 decreases lung tumor nodules in triple-negative breast cancer mice fed a low-fat diet." (PMID 33194597, 2020).
viral bronchiolitis (2 papers, 2022 to 2023). "The deletion of BMAL1 or disruption of the circadian clock environment exacerbates acute viral bronchiolitis caused by the Sendai and influenza A viruses in mice." (PMID 36505412, 2022).
vitamin D deficiency (2 papers, 2011 to 2017). A nutritional condition produced by a deficiency of VITAMIN D in the diet, insufficient production of vitamin D in the skin, inadequate absorption of vitamin D from the diet, or abnormal conversion of vitamin D to its bioactive metabolites. "A large co-expression network containing Npas2, Bmal1, and Vdr was observed to form with the Ti biomaterials, which was disintegrated by vitamin D deficiency." (PMID 28817668, 2017). "NPAS2 and Aryl hydrocarbon receptor nuclear translocator-like (ARNTL/Bmal 1) were upregulated around implant and diminished by vitamin D deficiency, whereas the expression pattern of Per2 was complementary." (PMID 21264318, 2011).
ZIKV infection (2 papers, 2019 to 2025). "Bmal-1 expression deficiency potentiated the severity ZIKV infection and contributed to endothelial barrier dysfunction and dysregulation of mitochondrial proteins." (PMID 40313764, 2025). "The impact of Bmal1 silencing and/or ZIKV infection on endothelial integrity was assessed by measuring transendothelial electrical resistance (TEER) and transendothelial transfer of 20 kDa FITC-dextran." (PMID 40313764, 2025). "ZIKV infection significantly decreased claudin-5, occludin, and ZO-1 protein levels in cells with silenced Bmal1 gene." (PMID 40313764, 2025). "We then evaluated the impact of circadian disruption by Bmal1 gene silencing on ZIKV infection of brain endothelial cells." (PMID 40313764, 2025). "ZIKV infection in endothelial cells with silenced Bmal1 gene upregulated MFF, indicating dysregulation of mitochondrial division." (PMID 40313764, 2025). "Silencing of Bmal1 combined with ZIKV infection resulted in alternations of the expression of several mitochondrial proteins, including the pDRP1s616/DRP1 ratio, MFF, and OPA1 in brain endothelial cells." (PMID 40313764, 2025). "In conclusion, the present study demonstrates the significant impact of circadian dysregulation achieved by Bmal1 silencing on the modulations of endothelial TJ proteins in ZIKV infection." (PMID 40313764, 2025). "Endothelial cells and endothelial cell-specific Bmal1 knock-out mice were subjected to Zika virus infection." (PMID 40313764, 2025). "Because gene expression changes can be only transitional, we also evaluated the impact of Bmal1 silencing and/or ZIKV infection on TJ protein expression." (PMID 40313764, 2025). "In the next series of experiments, we focused on the impact of ZIKV infection and/or Bmal1 silencing on the expression of TJ genes and proteins, such as claudin-5, occludin, zona occludens (ZO-1), and junctional adhesion molecule-3 (JAM-3)." (PMID 40313764, 2025). "Importantly, these changes were consistent with the downregulation of the expression of claudin-5, occludin, and ZO-1 proteins in endothelial cells subjected to ZIKV infections and Bmal1 silencing." (PMID 40313764, 2025). "Interestingly, ZIKV infection resulted in an increase in the protein expression of Bmal1, supporting our choice of silencing Bmal1 in the remaining series of experiments." (PMID 40313764, 2025). "Interestingly, ZIKV infection elevated the Bmal1 protein levels in brain endothelial cells as compared to Mock infection." (PMID 40313764, 2025). "To ascertain whether BMAL1 regulates DENV or ZIKV infection, we infected the KO Huh-7 cells and observed a significant reduction in the replication of both viruses in Bmal1 KO cells compared with WT." (PMID 30670689, 2019). "Therefore, we silenced the Bmal1 gene in in vitro studies and then used endothelial cell conditional Bmal1 knockdown mice for animal experiments to verify the involvement of the brain endothelium and mitochondrial dynamics in ZIKV infection of the adult brain." (PMID 40313764, 2025). "Relative TEER values (% of control) were not altered as a result of Bmal1 silencing and/or ZIKV infection." (PMID 40313764, 2025). "In summary, these data support a role for BMAL1 to regulate HCV, DENV and ZIKV infection." (PMID 30670689, 2019).
acne (1 paper, 2022). An inflammatory process of the sebaceous glands which is characterized by comedones, nodules, papules and/or pustules on the skin. "Here, we aimed to investigate the role of the central clock gene Bmal1 in acne-associated inflammation in mice." (PMID 35414779, 2022). "The finding that Bmal1 is a repressor of acne-associated inflammation herein helps us to understand why circadian disruption is a contributor to acne development." (PMID 35414779, 2022). "In summary, Bmal1 disruption is identified as a potential pathological factor of acne-associated inflammation." (PMID 35414779, 2022). "In the present study, we aimed to investigate the role of the central clock gene Bmal1 in acne-associated inflammation in mice." (PMID 35414779, 2022). "To assess the effect of Bmal1 on acne-associated inflammation, we used a mouse model of acne induced by P. acnes." (PMID 35414779, 2022). "In conclusion, Bmal1 disruption is identified as a potential pathological factor of acne-associated inflammation." (PMID 35414779, 2022). "We thus propose that Bmal1 is a critical component linking circadian clock to acne-associated inflammation." (PMID 35414779, 2022). "We found that Bmal1 and its target genes Rev-erbα, Dbp, Per1 and Cry2 were down-regulated in the skin of P. acnes-treated mice, suggesting a role of Bmal1 in the condition of acne." (PMID 35414779, 2022). "However, why skin Bmal1 is down-regulated in the acne model remains unaddressed." (PMID 35414779, 2022).
adrenal pheochromocytoma (1 paper, 2025). "Therefore, we established stable transfections of Rat adrenal pheochromocytoma cells (PC12) to overexpress the Bmal1 gene and a negative control using lentivirus." (PMID 40527853, 2025).
and stress-related disorders (1 paper, 2024). "Based on such a variety of functions, mutations or disruptions of BMAL1 may be predictors of pathologies including human affective and stress-related disorders." (PMID 39596543, 2024).
Atherosclerotic lesion (1 paper, 2024). A lesion associated with atherosclerosis, a multifactorial and multipart progressive disease manifested by the focal development within the arterial wall of lesions, that ranges from the development of a fatty streak, plaque progression, and plaque disruption. "Previous reports showed that Bmal1 affects the number of monocytes/macrophages infiltrating atherosclerotic lesions." (PMID 39664388, 2024).
atopic dermatitis (1 paper, 2023). "CC3, characterized by high expression of BMAL1 and CRY1, had a low prevalence of atopic dermatitis, which is associated with decreased activation of cytokine–cytokine receptor interaction pathways." (PMID 37108640, 2023).
atrial fibrillation (1 paper, 2025). A disorder characterized by an electrocardiographic finding of a supraventricular arrhythmia characterized by the replacement of consistent P waves by rapid oscillations or fibrillatory waves that vary in size, shape and timing and are accompanied by an irregular ventricular response. "For instance, based on the effect of BMAL1 on atrial fibrillation BMAL1 may play a role in inflammatory regulation, electrical remodeling, structural remodeling, and time therapy in patients with atrial fibrillation after PCI." (PMID 40429770, 2025).
benign prostatic hyperplasia (1 paper, 2022). A non-cancerous nodular enlargement of the prostate gland. "Since Bmal1 signaling is associated with the growth of the prostate, it is possible that it may also be involved in benign prostatic hyperplasia (BPH), as disruptions in turnover rates drive organ growth, and the prostate has a much higher turnover rate compared with the seminal vesicles." (PMID 36232573, 2022).
bladder cancer (1 paper, 2024). "We identified the circadian rhythm of the clock genes PER2 and BMAL1 and their impact on PPIX accumulation in bladder cancer cell lines UM-UC-3 and J82, as well as in mouse xenograft models." (PMID 39682298, 2024).
brain edema (1 paper, 2021). Increased intracellular or extracellular fluid in brain tissue. "Although clinical MRI scans suggested that all patients had peritumor brain edema to varying degrees, compared with the BMAL1− patients, patients with BMAL1+ expression were more likely to exhibit moderately severe or severe brain edema." (PMID 34815366, 2021).
breast tumor (1 paper, 2024). "Circadian disruption through BMAL1 deficiency inhibited the rate of cell invasion in both MCF-7 cells (P < 0.001) and primary luminal A breast tumor cells." (PMID 38319971, 2024).
calcific aortic valve disease (1 paper, 2024). "Additionally, calcific aortic valve disease (CAVD), which is common in the elderly, is associated with BMAL1 and calcification." (PMID 39267721, 2024).
cartilage disease (1 paper, 2025). Softening and degeneration of the CARTILAGE. "Global deletion of Bmal1 in mice has been implemented frequently in exploring bone/cartilage diseases, and loss of Bmal1 has been proved to be closely related to many aberrant manifestations in bone/cartilage." (PMID 39870641, 2025). "Bmal1-deficient mice exhibit different extents of manifestations that are related to bone/cartilage metabolism, and global Bmal1 knockout mice has been employed to depict the specific role of Bmal1 in regulating bone/cartilage diseases." (PMID 39870641, 2025).
cerebrovascular disease (1 paper, 2024). "Nevertheless, patients with cerebrovascular disease exhibit alterations in melatonin, cortisol, temperature, blood pressure, and the expression of the clock genes BMAL1, CLOCK, PER, and CRY." (PMID 38673986, 2024).
channelopathies (1 paper, 2026). "This shows that circadian disruption worsens underlying channelopathies, most likely due to mis regulation of circadian genes such Bmal1 and Rev-Erbα affect Kv ion channel expression and electrophysiological functions and cardiac tissue contraction pathways." (PMID 41548155, 2026).
chronic lymphocytic leukemia (1 paper, 2017). "For example, the circadian oscillation of gene expression is aberrant in leukemic cells, as BMAL1, PER1, and PER2 are down-regulated in patients with chronic lymphocytic leukemia." (PMID 28487473, 2017).
Cluster headache (1 paper, 2025). A type of headache characterized by repeated attacks of unilateral pain lasting 15 to 180 minutes and associated with local autonomic signs. "Lithium,indicated as a prophylactic treatment for cluster headache has been found to significantly increase the expression of Per2 and Cry1, and reduce the expression of Per3, Cry2, and Bmal1." (PMID 39560176, 2025).
colorectal adenocarcinoma (1 paper, 2023). The most common type of colorectal carcinoma. "At the same time, in the Sir Run Run Shaw Hospital (SRRSH) cohort, we first evaluated BMAL1 expression level in 84 primary colorectal adenocarcinoma specimens and examined the correlation between BMAL1 expression and clinicopathological parameters." (PMID 36806631, 2023).
congenital cataracts (1 paper, 2010). "Thus, both CLOCK and BMAL1 play an important role in lens physiology, strongly arguing that regulation of BMAL1:CLOCK transcriptional activity may be used for the prevention or treatment of age-dependent and possibly congenital cataracts." (PMID 21149897, 2010).
demyelinating disease (1 paper, 2025). A broad group of disorders that affect the myelin sheaths that cover the neurons. "In demyelinating diseases, while BMAL1 deficiency in myeloid cells affects inflammatory processes, its deficiency in OPCs or astrocytes disrupts OPC migration and remyelination at the site of injury." (PMID 41440117, 2025). "In an autoimmune encephalomyelitis model (an animal model of human demyelinating diseases), BMAL1 and time of day regulate the accumulation and activation of various immune cells." (PMID 41440117, 2025). "Thus, BMAL1 is involved in the pathogenesis of neurodevelopmental and demyelinating disorders (Table A1)." (PMID 41440117, 2025).
developmental delay (1 paper, 2025). "Remarkably, flies expressing variant cycle, the ortholog of BMAL1, also demonstrated deficits in short- and long-term memory, reminiscent of the highly prevalent developmental delay observed in our cohort." (PMID 40720646, 2025).
dry eye (1 paper, 2024). "Furthermore, melatonin, a circadian rhythm restorer, had a therapeutic effect on jet lag-induced dry eye by restoring the expression of BMAL1, which upregulated MUC4." (PMID 38956298, 2024).
E. coli infection (1 paper, 2024). "Supporting these observations, Bmal1-deficient macrophages exhibited enhanced LDH release by E. coli infection, which also induced caspase-1/-11-dependent cell death." (PMID 38297162, 2024).
emphysema (1 paper, 2016). "In fact, recent studies revealed that targeted deletion of BMAL1 in lung epithelium promotes inflammation and emphysema." (PMID 26753996, 2016).
Familial advanced sleep-phase syndrome (1 paper, 2011). "For example, in patients suffering from familial advanced sleep phase syndrome (FASPS) PER2 is hypophosphorylated but can still enter the nucleus and repress CLOCK/BMAL1 transactivation." (PMID 22194677, 2011).
focal epilepsy (1 paper, 2025). A seizure caused by a localized disorder. "In terms of clock genes, differences in the functionality of clock genes (BMAL1/CLOCK/Per/Cry) in various regions of the central nervous system can explain differences in seizure timing in focal epilepsy." (PMID 40438582, 2025).
follicular thyroid carcinoma (1 paper, 2022). "Another study demonstrated alterations of clock genes, overexpression of BMAL1, and downregulation of CRY2, in patients with follicular thyroid carcinoma and PTC34." (PMID 36335214, 2022).
HIV-1 infection (1 paper, 2023). The type species of lentivirus and the etiologic agent of acquired immunodeficiency syndrome (AIDS). "We noticed a temporal synchronicity in the transcriptional profiles of Bmal1 and HIV-1, leading us to assess the role of BMAL1 in HIV-1 infection." (PMID 37534138, 2023).
homocystinuria (1 paper, 2024). An autosomal recessive inherited metabolic disorder caused by mutations in the CBS, MTHFR, MTR, and MTRR genes. "This reveals a direct link between the clock gene, BMAL1, and homocystinuria in de-activating the normal circadian cycle." (PMID 39727952, 2024).
Hyperbilirubinemia (1 paper, 2019). An increased amount of bilirubin in the blood. "Further, Bmal1 ablation caused a loss of circadian time-dependency in bilirubin clearance and sensitized mice to chemical induced-hyperbilirubinemia." (PMID 31410205, 2019). "We further showed that the circadian clock gene Bmal1 controlled the rhythmic expressions of Ugt1a1 and Mrp2 via direct transactivation, thus regulated the sensitivity of mice to chemical induced-hyperbilirubinemia." (PMID 31410205, 2019). "Bmal1 ablation abrogated circadian time-dependent bilirubin clearance and sensitized mice to hyperbilirubinemia." (PMID 31410205, 2019). "However, the circadian time differences in hyperbilirubinemia ceased to exist in Bmal1-/- mice consistent with equal protein levels of Ugt1a1 (and Mrp2) at both circadian time points in the genetically modified mice." (PMID 31410205, 2019). "We also assessed the role of Bmal1 in phenylhydrazine (PHZ)-induced hyperbilirubinemia." (PMID 31410205, 2019). "Moreover, Bmal1 ablation sensitized mice to hyperbilirubinemia." (PMID 31410205, 2019). "The more severe hyperbilirubinemia agreed well with a higher level of hepatotoxicity (i.e., higher hepatic levels of ALT, AST and inflammatory cytokines) in Bmal1-/- mice." (PMID 31410205, 2019). "Similarly, Bmal1 ablation sensitized mice to PHZ-induced hyperbilirubinemia (high levels of plasma and liver UCB in Bmal1-/- mice)." (PMID 31410205, 2019). "However, hyperbilirubinemia was more severe (significantly higher levels of plasma and liver UCB) in Bmal1-/- than in wild-type mice." (PMID 31410205, 2019).
Hypercholesterolemia (1 paper, 2021). An increased concentration of cholesterol in the blood. "Thus, intestinal deficiency of Bmal1 also protects mice against hypercholesterolemia induced by a HFD." (PMID 34493722, 2021).
Hyperinsulinemia (1 paper, 2025). An increased concentration of insulin in the blood. "On a chow diet, adipocyte-specific loss of Bmal1 impaired glucose tolerance and caused compensatory hyperinsulinemia despite normal body weight across groups." (PMID 41279878, 2025).
hypogonadism (1 paper, 2018). A disorder characterized by decreased function of the gonads. "However, Bmal1−/− mice did not exhibit a high bone mass (HBM), which may be explained by hypogonadism, a condition that increases bone resorption." (PMID 29765408, 2018).
idiopathic hypersomnia (1 paper, 2014). Idiopathic hypersomnia is a sleep disorder classified in two forms: idiopathic hypersomnia with long sleep time and idiopathic hypersomnia without long sleep time. "Therefore deregulation of BMAL1 gene as a common element participating in both circadian and sleep regulatory processes might be an indicator for idiopathic hypersomnia." (PMID 24454829, 2014).
Immunodeficiency (1 paper, 2020). Failure of the immune system to protect the body adequately from infection, due to the absence or insufficiency of some component process or substance. "When subcutaneously injected in the flanks of immunodeficiency mice, both Bmal1 KO and WT ESCs were able to efficiently form teratomas of similar size." (PMID 32284354, 2020).
intestinal polyp (1 paper, 2022). Discrete abnormal tissue masses that protrude into the lumen of the intestine. "A statistically significant increase in intestinal polyp incidence was identified in Apc+/−;Bmal1−/− mice versus Apc+/− animals." (PMID 35947664, 2022).
intestinal polyposis (1 paper, 2022). "Unexpectedly, when male and female mice were euthanized at 9 to 10 months of age, greater intestinal polyposis was observed in Apc+/−;Bmal1−/− mice versus Apc+/− mice." (PMID 35947664, 2022).
knee osteoarthritis (1 paper, 2024). "Studies have shown that patients with knee osteoarthritis exhibited lower expression of the clock genes NR1D1 and BMAL1 in knee joint cartilage compared to normal individuals." (PMID 39010104, 2024).
lactic acidosis (1 paper, 2020). Metabolic acidosis characterized by the accumulation of lactate in the body. "BMAL1 is also reduced by lactic acidosis and recovered by exchanging media or adding NaHCO3." (PMID 32316196, 2020).
learning disability (1 paper, 2025). A group of disorders that affect a person's ability to learn or process specific types of information which is in contrast to his/her apparent level of intellect. "The BMAL1 p.(Lys405Ter) variant in Individual #6 was inherited from a father who had a history of learning disability and tics and was unable to read and write." (PMID 40720646, 2025).
lipodystrophy (1 paper, 2011). A congenital or acquired disorder characterized by abnormal loss or redistribution of the adipose tissue in the body. "Metabolic disorder in Bmal1 -/- mice was induced as a result of lower adipogenesis activity, as observed in lipodystrophy." (PMID 21966465, 2011).